SHOX (SHOX homeobox)
Diseases named in the same sentence as SHOX in open-access papers (continued):
Sharing a sentence is not in itself a finding about the gene and the disease.
Klinefelter syndrome (4 papers, 2016 to 2022). A sex chromosome disorder caused by the presence of an extra X chromosome in the male karyotype. "Overdosage of the SHOX gene by large duplications of SHOX exons and cis-acting enhancers is implicated in the tall stature of Klinefelter syndrome (47, XXY) and triple-X syndrome (47, XXX)." (PMID 36611397, 2022). "Gene dosage of the SHOX locus has previously been shown to determine height: SHOX deficiency causes short stature, whereas SHOX overdosage has been linked to tall stature in Klinefelter syndrome." (PMID 27861128, 2016).
Intellectual disability (3 papers, 2015 to 2023). "The PAR1 genes, including SHOX, play essential roles in the phenotypic traits associated with TS, including short stature, wrist deformity, and intellectual disabilities." (PMID 37408200, 2023). "The PAR1 genes, including SHOX, play essential roles in the phenotypic traits associated with TS, including short stature, Madelung’s wrist deformity, and intellectual disabilities." (PMID 37408200, 2023). "Previous studies reported that duplication involving the SHOX gene would lead to short stature, intellectual disability, and developmental delay." (PMID 34722424, 2021).
scoliosis (3 papers, 2023 to 2025). A congenital or acquired spinal deformity characterized by lateral curvature of the spine. "The SHOX (short stature homeobox) gene, known for its role in growth and development, has been associated with various skeletal abnormalities, including scoliosis, due to its influence on vertebral development." (PMID 37965575, 2023). "In the case of SHOX haploinsufficiency, there is an increased risk of scoliosis and wrist deformities, which may benefit from early orthopedic evaluation and intervention." (PMID 40723048, 2025). "In TS, it results in SHOX haploinsufficiency, which could influence different abnormalities such as Madelung’s deformity, scoliosis or micrognathia." (PMID 37765128, 2023).
triple X syndrome (3 papers, 2009 to 2022). "The SHOX gene lies within the pseudo-autosomal region and overdosage, as a result of triple X syndrome, when combined with estrogen deficiency, has been suggested to be responsible for the often tall stature in women with three X chromosomes." (PMID 19830242, 2009).
Bloom syndrome (2 papers, 2022). Bloom syndrome (BSyn) is a rare chromosomal breakage syndrome characterized by a marked genetic instability associated with pre- and postnatal growth retardation, facial sun-sensitive telangiectatic erythema, increased susceptibility to infections, and predisposition to cancer. "Interestingly to note, BLM, another member of the RecQ helicase family implicated in Bloom syndrome, also failed to stimulate SHOX promoter activity." (PMID 36587229, 2022).
developmental delay (2 papers, 2011 to 2021). "They reason that, as none of their patients had congenital anomalies apart from their skeletal features, and none had developmental delay, if SHOX acts outside of the musculo-skeletal system, its extra skeletal functions are redundant with other genes; perhaps SHOX2 or other HOX genes." (PMID 21731768, 2011).
dysplasia (2 papers, 2018 to 2021). A usually neoplastic transformation of the cell, associated with altered architectural tissue patterns. "The HOXA11/HOXD11 genes are particularly intriguing candidates as potential upstream regulators of SHOX since their mutation in mice causes zeugopodal truncations similar to that of Langer mesomelic dysplasia patients." (PMID 30250174, 2018).
osteosarcoma (2 papers, 2017 to 2021). A usually aggressive malignant bone-forming mesenchymal neoplasm, predominantly affecting adolescents and young adults. "On the other hand, previous studies in U2OS osteosarcoma cells, human primary oral fibroblasts, and chondrocytes showed that overexpression of SHOX induced cell cycle arrest at G2/M phase and the activation of apoptotic pathway." (PMID 28642734, 2017). "In human osteosarcoma cells, the induction of SHOX expression elevates CDKN1A and CDKN1B levels." (PMID 34122528, 2021).
Short stature (2 papers, 2021 to 2023). A height below that which is expected according to age and gender norms. "In summary, we uncovered a compound heterozygous variant in the SHOX (c.577G > A) gene in a female Chinese child with familial idiopathic short stature, which inherited from his father." (PMID 37832088, 2023). "Entire gene deletions and/or mutations causing loss of protein function in SHOX, IGF1R, NPPC, and NPR2 have been reported in familial short stature with various degrees of severity 18,37–40." (PMID 33850126, 2021).
Williams-Beuren Syndrome (2 papers, 2013 to 2019). "Five patients were previously diagnosed with Temple syndrome (uniparental disomy of chromosome 14), Williams syndrome (7q11.23 microdeletion) or deletions in SHOX (n = 3)." (PMID 30838190, 2019).
autism spectrum disorder (1 paper, 2022). A spectrum of developmental disorders that includes autism, and Asperger syndrome. "SHOX/SHOX enhancer deletions cause short stature and skeletal abnormalities (#249700, #127300, #300582); microduplications in the pseudoautosomal region including SHOX appear to be rare and have been related to autism spectrum disorders and neurodevelopmental pathologic conditions." (PMID 35407632, 2022).
Blepharophimosis (1 paper, 2015). A fixed reduction in the vertical distance between the upper and lower eyelids with short palpebral fissures. "Instead enhancer loss occurs in Léri-Weill syndrome and BPES (Blepharophimosis, ptosis, epicanthus inversus syndrome), in which deletions of SHOX (Léri-Weill) or FOXL2 (BPES) enhancers are reported." (PMID 25701871, 2015).
clubfoot (1 paper, 2023). The most common congenital deformation of the foot, occurring in 1 of 1,000 live births. "Microduplications of the pseudo-autosomal chromosome region Xp22.33 (Par1) containing SHOX have been found in about 1% of clubfoot patients." (PMID 37964341, 2023).
cognitive deficits (1 paper, 2007). "In addition, high resolution genomic technologies such as array comparative genomic hybridization may detect submicroscopic deletions associated with TS cognitive deficits that would identify the causative gene(s), as was the case for short stature due to SHOX deletion." (PMID 17517138, 2007).
Immunodeficiency (1 paper, 2020). Failure of the immune system to protect the body adequately from infection, due to the absence or insufficiency of some component process or substance. "The short arm of X harbors the short stature-homeobox gene (SHOX on Xp22.33) and lymphogenic gene (forkhead box P3, FOXP3 on Xp11.23), which are associated with stature and immunodeficiency or polyendocrinopathy." (PMID 32684981, 2020).
mantle cell lymphoma (1 paper, 2016). Mantle cell lymphoma is a rare form of malignant non-Hodgkin lymphoma affecting B lymphocytes in the lymph nodes in a region called the ``mantle zone''. "Additionally, deletion of SHOX has also been reported in mantle cell lymphoma." (PMID 27655702, 2016). "Conversely, LOH of CSF2RA, along with SHOX and CRLF2, due to deletion in a portion of the PAR has been reported in mantle cell lymphoma." (PMID 27655702, 2016). "LOH in a region of the PAR, which results in deletion of SHOX, CRLF2, and CSF2RA, has been observed in mantle cell lymphoma." (PMID 27655702, 2016).
Mesomelia (1 paper, 2016). Shortening of the middle parts of the limbs (forearm and lower leg) in relation to the upper and terminal segments. "Mesomelia and MD were present only in those individuals carrying damaging variants in both SHOX and CYP26C1." (PMID 27861128, 2016).
MRKH syndrome (1 paper, 2021). "Moreover, MLPA assay detected a novel duplication of CNE-2 SHOX enhancer in Patient 64, which has not been previously associated to MRKH syndrome." (PMID 33432050, 2021).
ovarian dysfunction (1 paper, 2019). The inability of the ovaries to function. "Only a few cases have been published and in most of them the reported patients present ovarian dysfunction, tall stature, and overdosage of the SHOX gene with locus Xp22.33." (PMID 31093387, 2019).
premature ovarian failure (1 paper, 2011). "Furthermore, SHOX duplication in conjunction with chromosomal deletions on the long arm of X (Xq) has been reported in four females, one of whom had been reported with premature ovarian failure." (PMID 21806840, 2011).
Rett syndrome (1 paper, 2020). A severe neurodevelopmental disorder affecting the central nervous system.
X-linked chondrodysplasia punctata (1 paper, 2011). X-linked form of chondrodysplasia punctata. "Molecular mapping showed the maternally-derived deletion included SHOX, ARSE (the gene mutated in X-linked chondrodysplasia punctata) and the putative mental retardation locus mental retardation, X-linked 49 (MRX49)." (PMID 21731768, 2011).
skeletal dysplasia (12 papers, 2011 to 2023). Any Mendelian diseases that affects growth and development of the skeleton. "Homozygous defects in SHOX gene cause Langer mesomelic dysplasia, a rare skeletal dysplasia with severe short stature and limb aplasia or hypoplasia of the ulna and fibula." (PMID 30864634, 2019). "SHOX haploinsufficiency is known to result from heterozygous loss-of-function variants with pseudo-autosomal dominant inheritance, while biallelic SHOX loss-of-function variants cause the more severe skeletal dysplasia, Langer mesomelic dyschondrosteosis (LMD)." (PMID 37107635, 2023). "While LMD, which is a much more severe skeletal dysplasia than LWD, results from biallelic (homozygous or compound heterozygous) SHOX pathogenic variants, SHOX haploinsufficiency is associated with ISS and LWD." (PMID 32295321, 2020). "The nonspecific and variable phenotype of SHOX deficiency frequently leads to diagnostics such as skeletal dysplasia with disharmonious short stature, ISS, or SGA." (PMID 36611397, 2022). "Moreover, partial SHOX duplications appeared to have a more deleterious effect on skeletal dysplasia and height gain than complete SHOX duplications." (PMID 26884814, 2016). "Mutations in the homeobox gene SHOX cause SHOX deficiency, a condition with clinical manifestations ranging from short stature without dysmorphic signs to severe mesomelic skeletal dysplasia." (PMID 27861128, 2016).
neoplasia (3 papers, 2015 to 2022). "Being that several PAR genes are implicated to function as tumor suppressors, such as PPP2R3B, SHOX, SLC25A6, ASMT, and DHRSX, they serve as prime candidates for further investigation and may hold the greatest therapeutic promise." (PMID 27655702, 2016).
cancer (2 papers, 2014 to 2025). A tumor composed of atypical neoplastic, often pleomorphic cells that invade other tissues. "The expressions of SHOX, RASSF1A and PTGER4 proteins in cancer tissues and para-carcinoma tissues were detected by immunohistochemistry, and methylation status of SHOX, RASSF1A and PTGER4 genes in peripheral venous blood was detected by sulfite-modified real-time fluorescence quantification." (PMID 40386526, 2025). "However, a contribution of SHOX in other CTGF-associated conditions such as fibrotic disease, inflammation and cancer is not known." (PMID 24887312, 2014).
autosomal dominant disease (1 paper, 2021). Autosomal dominant form of disease. "In addition, an unknown significance of Xp22.33 microduplication was detected, containing SHOX/SHOXY gene, which was related to autosomal dominant diseases of Leri–Weill cartilage osteogenesis disorder due to gene mutation or deletion." (PMID 34722424, 2021).
neurodevelopmental disorder (1 paper, 2024). A behavioral and cognitive disorder with onset during the developmental period that involves impaired or aberrant development of intellectual, motor, or social functions. "One study has also found a link between neurodevelopmental disorders and microduplications at the SHOX locus, suggesting that such perturbations may alter neural development or function." (PMID 39389973, 2024).
SHOX also shares sentences with these, for which no sentence is quoted: Prader-Willi syndrome (4 papers); genetic disorder (3); autism (2); growth disorders (2); microcephaly (2); Asperger syndrome (1); brain malformations (1); cardiac disease (1); chondrodysplasia (1); chromosomal disorder (1); congenital adrenal hyperplasia (1); endometriosis (1); Fanconi syndrome (1); fragile X syndrome (1); Gitelman syndrome (1); growth failure (1); Hodgkins lymphoma (1); hypochondroplasia (1); hypogonadism (1); hypophosphatemic rickets (1); ichthyosis (1); idiopathic familial short stature (1); Kallmann syndrome (1); leukemia (1); malnutrition (1); medulloblastoma (1); mesomelic dysplasia (1); muscular hypertrophy (1); Noonan syndrome (1); polyendocrinopathy (1).
A further 7 diseases each share a sentence with SHOX in 1 paper.